RNA5SP141 (RNA, 5S ribosomal pseudogene 141)
Synonyms: RN5S141
Gene: Ribosomal RNA pseudogene on chromosome 3 (134,783,436 to 134,783,555, reverse strand). Ensembl gene ENSG00000201413.
Diseases named in the same sentence as RNA5SP141 in open-access papers:
RNA5SP141 is named in the same sentence as 2 diseases in open-access papers, as found by Europe PMC text mining. Sharing a sentence is not in itself a finding about the gene and the disease. The quoted sentences say what the papers report.
Viral infection (1 paper, 2024). "Viral infection results in the downregulation of cellular 5S ribosomal RNA pseudogene 141 (RNA5SP141)-interacting proteins, thereby allowing RNA5SP141 to bind RIG-I and induce antiviral immune responses." (PMID 38940585, 2024).
infection (1 paper, 2025). The state of being infected such as from the introduction of a foreign agent such as serum, vaccine, antigenic substance or organism. "Furthermore, one of these transcripts, RNA5SP141, has been shown to be relocalized from the nucleus to the cytoplasm during infection and that silencing of this transcript strongly attenuates the antiviral response to HSV-1." (PMID 40198737, 2025).